DUOX2 (dual oxidase 2)
Diseases named in the same sentence as DUOX2 in open-access papers (continued):
Sharing a sentence is not in itself a finding about the gene and the disease.
cancer (28 papers, 2013 to 2025). A tumor composed of atypical neoplastic, often pleomorphic cells that invade other tissues. "As a member of the NADPH oxidase family, DUOX2 has been identified as being closely associated with the generation of ROS and the chemoresistance of cancer cells." (PMID 40875107, 2025). "Except in cancer, high levels of DUOX2 caused the release and accumulation of reactive oxygen species, which induced the activation of the pro-inflammatory cytokine, thus leading to inflammation in the body." (PMID 39224819, 2024). "More generally, defects in each of the players of the LoL-DDR response described here (NF-κB, PARP1, FOXO1, DUOX1 and DUOX2) share common phenotypes, such as defects in cell homeostasis and metabolism, aging and cancer predisposition." (PMID 36869180, 2023). "Studies have determined that DUOX2 is up-regulated in many cancers, leading to the accumulation of H2O2 and DNA damage through NF-κB signaling." (PMID 39224819, 2024). "Mitochondria and NOXs family, including NOX1, NOX2, NOX3, NOX4, NOX5, DUOX1, and DUOX2, are two important sources of ROS production in cancer cells." (PMID 35418176, 2022). "Knockdown of DUOX2 using siRNA technology revealed significant inhibition of cell proliferation, migration, and invasion of cancer cells in vitro." (PMID 33748270, 2021). "Recent oncological researches have revealed that DUOX2 is widely investigated and showed overexpression in many malignant tumors." (PMID 33748270, 2021). "The results showed that the transcriptional levels of DUOX2 expression were significantly increased in cancer tissues when compared to matched normal tissues." (PMID 33748270, 2021). "Our data indicate that expression of DUOX2, an enzyme involved in the production of hydrogen peroxide, increases the odds of preventing cancer dissemination in response to low dose radiation and conventional chemotherapy." (PMID 34439340, 2021). "To validate these data, we next performed immunohistochemistry (IHC) analysis of DUOX2 expression on a panel of human stomach samples from normal, premalignant and cancers tissues with progressive grades." (PMID 34439340, 2021). "Mitochondria and NADPH oxidases of the Nox family including NOX1, NOX2, NOX3, NOX4, NOX5, DUOX1 and DUOX2, are two important sources of ROS production in cancer cells." (PMID 30755243, 2019). "Although DUOX2 expression has been observed in human cancer tissues, it is also highly expressed in normal tissues, indicating that DUOX2 is not overexpressed in human cancer tissues." (PMID 29065504, 2017). "Third, in vitro studies demonstrated that IL-17A and duodenal ILC3s induce DUOX2/DUOXA2 expression, with the former specifically upregulating Duox2 protein, thereby driving mitochondrial-independent ROS production and DNA damage, a key mechanism in cancer progression." (PMID 40280932, 2025). "Some studies suggest that DUOX2 may enhance cancer cell resistance to 5-FU by promoting ROS production, which triggers epithelial-mesenchymal transition in CRC cells." (PMID 40875107, 2025). "Notably, it was demonstrated that in the presence of a dysbiotic microbiota, DUOX2 potentiates intestinal tumorigenesis, thus supporting the role of DUOX2 in epithelial proliferation and its dysregulation in cancer pathogenesis." (PMID 37891968, 2023). "DUOX2 has been reported to highly express in several types of cancers." (PMID 33748270, 2021). "The goal of the present study was to generate monoclonal antibodies against the human Duox2 protein to provide reagents that would be useful for investigating the role of Duox2 in cancer, where alterations in oxidant tone play a critical role in cell growth and proliferation." (PMID 23404210, 2013). "Moreover, DUOX2 was reported to have anti-cancer drug resistant activities through EMT42." (PMID 33483567, 2021).
cancer (continued). "In addition, it is reported that increase of DUOX2 could directly mediate the production of ROS, therefore accelerate development of gastrointestinal and respiratory diseases and cancer." (PMID 35096875, 2021). "To date, the interconnection between H2O2 signaling and EMT in cancer is well established, and the role of H2O2 producers NADPH oxidase 4 (NOX4), dual oxidase 1 (DUOX1) and DUOX2 in cell motility and metastasis in cancer biology has been reviewed." (PMID 35873564, 2022). "The abnormal expressions of NOS2, DUOX2/DUOXA2, ESR1, EGFR, MYC, and AKT1, which are being discussed in this study, have been confirmed to be related to cancer." (PMID 33299870, 2020). "High quality, commercial monoclonal antibodies against Duox2 are not available; and thus, Duox protein expression has not been widely examined in cancers of any histology or chronic inflammatory conditions in comparison to normal tissues." (PMID 23404210, 2013).
infection (13 papers, 2007 to 2025). The state of being infected such as from the introduction of a foreign agent such as serum, vaccine, antigenic substance or organism. "High ROS in Camp+/+ during infection was confirmed by elevated levels of dual oxidase 2 (Duox2) mRNA, an essential source of hydrogen peroxide, whereas C. rodentium-infected Camp-/- colonic epithelium showed minimal Duox2 expression." (PMID 40735968, 2025). "DUOX2 activation in parasites increases during the course of infection up to day 14, when emerging into the intestinal lumen." (PMID 35508502, 2022). "Expression levels of duox-2, an important gene in mosquito reactive oxygen species production, were unaffected by wMel infection, diet, or diet x Wolbachia interaction (GLM; P < 0.05)." (PMID 27893736, 2016). "Duox2 is mainly involved in responses to infection and inflammation, whereas Duox1 plays an important role in defense and mucus production." (PMID 23691121, 2013). "Between day 12 and day 14 after infection, the adult parasites shift their metabolism towards oxidative phosphorylation/aerobic glycolysis-like pathways and show increased levels of DUOX2 activation (oxidative burst), indicating defense mechanisms, possibly against the host." (PMID 35508502, 2022). "Whether CFTR/DUOX2 NADPH axis differentially regulates sterile or infection-induced neutrophilic inflammation remains to be addressed." (PMID 32849617, 2020). "Another source of ROS during IV infection that belongs to the Nox/Duox family is Duox2." (PMID 30049972, 2018). "An approximate 12- and 8-fold up-regulation of dual oxidase 2 (DUOX2) and DUOXA2 respectively was observed between the rats that received a secondary parasite challenge and those that received the sham infection." (PMID 21698235, 2011). "Indeed, the production of ROS is essential to control infection, as knock-down of NOX2 expressed in immune cells, or inhibition of DUOX2-mediated epithelial ROS production resulted in uncontrolled bacteria proliferation in zebrafish and mouse models." (PMID 37619220, 2023). "Similarly, infection-induced expression of Duox2 and Gpx2 was also attenuated by dietary chicory, albeit not significant." (PMID 37316905, 2023). "Transcriptomic analyses revealed a negative ROS balance in Camp-/- littermates colons during infection, with lesser synthesis of key ROS enzymes, such as NADPH oxidases (Nox4 and Duox2), and increased ROS detoxification." (PMID 40735968, 2025).
gastrointestinal disease (2 papers, 2016 to 2021). A disease that occurs in the gastrointestinal system, excluding the hepatobiliary system. "DUOX2 is H2O2-generating enzyme and could be a major source of ROS, which have been implicated in the pathogenesis of gastrointestinal disease." (PMID 26839536, 2016). "Particularly, loss of function and excessive activity of enzymes producing reactive oxygen species DUOX2 and NOX1 have been suggested to contribute to gastrointestinal disease progression." (PMID 33930606, 2021).
inflammation (2 papers, 2021 to 2023). Aberrant reaction of the microcirculation characterized by movement of fluid and leukocytes from the blood into extravascular tissues. "DUOX2-microbiome interactions in humans were investigated by paired analyses of mucosal DUOX2 expression and fecal microbiome data in patients with intestinal inflammation." (PMID 37891968, 2023). "By analyzing transcriptomics data from mucosal biopsies of human IBD patients from multiple clinical studies, we found increased DUOX2 expression irrespective of age or type of intestinal inflammation, thus corroborating DUOX2 as a risk gene for IBD and related inflammatory diseases." (PMID 37891968, 2023).
respiratory diseases (2 papers, 2021 to 2025). "In the context of respiratory diseases, with respiratory viral infections as an example, Ducquin demonstrated that DUOX2 selectively regulates the cytokines and chemokines secreted by epithelial cells." (PMID 40830794, 2025).
autosomal recessive disease (1 paper, 2022). Autosomal recessive form of disease. "Nonetheless, similar to the DUOX2 missense substitution detected in TOKAI-IRUD-1290, it might be possible to diagnose more cases with autosomal recessive diseases in the near future, wherein the pathogenic variants inherited from one parent become homozygous due to isodisomy." (PMID 36028527, 2022).
bacterial infection (1 paper, 2022). "Dual oxidase 2 (DUOX2) protein during bacterial infection has been shown to be involved in NOD2-dependent ROS production." (PMID 36146565, 2022).
genetic disorders (1 paper, 2012). "In addition, other genetic disorders may be more effective than TPO mutations in CH patients with dyshormonogenesis including the sodium symporter (NIS) gene, the pendrin gene (PDS), the thyroid oxidase gene 2 (THOX2 or DUOX2), and thyroglobulin gene." (PMID 22919382, 2012).
infectious disease (1 paper, 2022). A disorder directly resulting from the presence and activity of a microbial, viral, or parasitic agent in humans. "Two members of the NADPH oxidase (NOX) family, including the DUOX1 and DUOX2 proteins, are potential therapeutic targets against infectious diseases caused by the influenza A virus." (PMID 36093436, 2022).
DUOX2 also shares sentences with these, for which no sentence is quoted: thyroid dyshormonogenesis 6 (3 papers); intestinal inflammation (2); ovarian carcinoma (2); Pendred syndrome (2); primary biliary cholangitis (2); Sensory hearing loss (2); thyroid hypoplasia (2); thyroid tumor (2); acute pancreatitis (1); allergic asthma (1); Angelman syndrome (1); Central hypothyroidism (1); chondrodysplasia (1); colon polyps (1); diseases of the esophagus (1); Down syndrome (1); dwarfism (1); endocervical adenocarcinoma (1); endocrine system disorder (1); enteropathies (1); euthyroid goiter (1); gastric ulcer (1); human papillomavirus infection (1); Hyperoxaluria (1); Hyperphenylalaninemia (1); hyperthyroidism (1); Immunodeficiency (1); infectious colitis (1); intestinal infection (1); iron overload (1).
A further 17 diseases each share a sentence with DUOX2 in 1 paper.